PTPRM (protein tyrosine phosphatase receptor type M)
Diseases named in the same sentence as PTPRM in open-access papers (continued):
Sharing a sentence is not in itself a finding about the gene and the disease.
cancer (continued). "Based on recent experimental studies, showing PTPRM knockdown or induced PTPRM methylation to increase STAT3 phosphorylation in cancer cells, we hypothesized PTPRM hemizygosity as a result of the interstitial 18p deletion in the triplets to cause increased STAT3 phosphorylation in immune cells." (PMID 39359478, 2024). "STAT3 inactivation is catalysed by PTPRM dephosphorylation and leads to cancer cell death, therefore errors incurred in STAT3 dephosphorylation, such as promoter hypermethylation induced PTPRM transcriptional silencing, may lead to cancer initiation and progression with poor clinical prognosis." (PMID 38475971, 2024). "Indeed, PTPRM has been shown to inhibit cancer cell proliferation, migration, and invasion." (PMID 31900385, 2020). "Currently, the role played by PTPRM in cancer remains unknown." (PMID 23185569, 2012). "The levels of several mRNAs that code for surface proteins with roles in cancer were similarly upregulated, including ALK, PTPRM, PTPRF, PTPRK, and SVEP1." (PMID 39335212, 2024). "PTPRM is a member of the protein tyrosine phosphatase (PTP) family, a large family of enzymes; it is involved in cell–cell adhesion in epithelial and cancer cells and regulates cell growth, differentiation, and oncogenic transformation." (PMID 35626106, 2022). "Thus PTPRM suppresses STAT3 signaling in DDIAS-knockdown cells, suggesting that DDIAS promotes the IL-6–mediated STAT3 signaling in malignant cancer cells by inhibiting the PTPRM function." (PMID 31900385, 2020).
adenocarcinoma (1 paper, 2015). A common cancer characterized by the presence of malignant glandular cells. "Of the canonical changes noted, promoter (PR) DM loci with reciprocal changes in expression in adenocarcinomas included HBEGF, AGER, PTPRM, DPT, CST1, MELK; DM GB loci with concordant changes in expression included FOXM1, FERMT1, SLC7A5, and FAP genes." (PMID 26683690, 2015).
PTPRM also shares sentences with these, for which no sentence is quoted: lymph node metastasis (3 papers); astrocytoma (2); breast tumors (1); colorectal (1); colorectal tumors (1); developmental delay (1); diabetes (1); E. coli infection (1); gastric cancer (1); Graves disease (1); lung adenocarcinoma (1); malignant glioma (1); marijuana dependence (1); metastasis (1); neurodevelopmental disorder (1); neurological disorders (1); nicotine dependence (1); Salmonella Infections (1); thyroid disease (1); toxoplasmosis (1); viral myocarditis (1).